RNU6-467P (RNA, U6 small nuclear 467, pseudogene)
Gene: Small nuclear RNA gene on chromosome 17 (20,323,001 to 20,323,110, forward strand). Ensembl gene ENSG00000276577.
Homologues: Orthologues: chimpanzee U6 (100% identical), macaque U6 (87% identical), mouse Gm22997 (76% identical), pig U6 (75% identical), pig U6 (72% identical), rat U6 (71% identical). Paralogues in human: RNU6-405P (99% identical), RNU6-1178P (92% identical), RNU6-819P (82% identical), RNU6-333P (81% identical), RNU6-490P (81% identical), RNU6-480P (80% identical), RNU6-774P (80% identical), RNU6-127P (79% identical), RNU6-1318P (79% identical), RNU6-38P (79% identical), RNU6-845P (79% identical), RNU6-1237P (78% identical), and 1285 more.